CD96 (CD96 molecule)
Diseases named in the same sentence as CD96 in open-access papers (continued):
Sharing a sentence is not in itself a finding about the gene and the disease.
cancer (continued). "Although the function of CD96 in the pan-cancer pattern has been partly explored, further demonstration of a certain relationship between CD96 and cancers is very important." (PMID 36043142, 2022). "In pan-cancer analysis, CD96 was found to affect immune cell infiltration and malignant properties, thereby significantly affecting the prognosis of various cancers." (PMID 35223835, 2022). "This review provides an overview of the CD226 axis in the context of cancer, with a focus on the status of immunotherapeutic strategies (TIGIT, CD96, and PVRIG) and their underlying biology (i.e., cis/trans interactions)." (PMID 35812451, 2022). "CD96 participates in a variety of immune responses, controls immune cell infiltration, and affects the malignant properties of various cancers." (PMID 35909123, 2022). "The expression of CD96 was shown to be significantly elevated in various cancers and to correlate positively with levels of infiltration of several types of immune cells, including CD8+ T cells, DCs, macrophages, monocytes, NK cells, neutrophils, and Tregs." (PMID 36177001, 2022). "The inhibitory checkpoint receptors TIGIT (T cell Ig and ITIM domain) and CD96 are upregulated by T and NK cells following activation when exposed chronically to antigen in settings like cancer." (PMID 34150627, 2021). "Treatment with anti-CD96 mAb can inhibit the progression and metastasis of melanoma, lung carcinoma and prostate carcinoma through promoting NK cell anti-cancer activity in an IFN-γ-dependent manner." (PMID 35008589, 2021). "In cancer patients, increased CD96 expression has been observed on NK cells from ovarian cancer ascites compared to peripheral blood NK cells from healthy donors." (PMID 34503073, 2021). "Previous review has elucidated the mechanism of CD226/TIGIT/CD96 pathway, addressing the important role of these membrane-sided signal receptors in multiple cancer types." (PMID 33680972, 2021). "To understand how CD96 impacting cancer patient prognosis, we used the PrognoScan database to analyze the relationship between CD96 and the survival outcomes of cancer patients." (PMID 33680972, 2021). "This suggests that CD96 can affect patient prognosis by influencing cancer malignant characteristics." (PMID 33680972, 2021). "HPA, TCGA, GEO, GTEx, Oncomine, TIMER2.0, PrognoScan, Linkedomics, Metascape, and GEPIA2 databases were used to analyze CD96 in cancers." (PMID 33680972, 2021). "As a relatively recent identified immune checkpoint, CD96-targeted therapy for cancer is only evaluated in preclinical studies for the time being." (PMID 35008589, 2021). "For example, high expression of CD96 in BC tissue, which was discovered in 1992, indicates high immune cells infiltration and hence killing of cancer cells." (PMID 34268106, 2021). "Together, these results indicated a malignant biological property and complicated prognostic value for CD96 in pan-cancer." (PMID 33680972, 2021). "According to the expression, survival, and mutation analysis, we observed significant but contradictory roles of CD96 in different cancers." (PMID 33680972, 2021). "A novel immune checkpoint receptor target, CD96, has recently entered the limelight in current cancer immunotherapies shown to inhibit natural killer (NK) cells." (PMID 32695752, 2020). "In fact, the role of TIGIT and CD96 in NK cell exhaustion in various cancers is under investigation, and further revelations are needed to establish their potential for targeting either as monotherapy or in combination with other checkpoints." (PMID 32117298, 2020). "These mice are also resistant to a experimental lung metastasis model, suggesting a potential therapeutic role of CD96 blockade in cancer treatment." (PMID 31360302, 2019). "exhibited that CD96 played a vital but contradictory role in different cancers." (PMID 41181119, 2025).
cancer (continued). "Notably, CD96 exhibited significant predictive ability for OS in 9 cancers (all P < 0.05), CSH1 demonstrated significance in 3 cancers (all P < 0.05), and OAS1 emerged as a significant predictor in 10 cancers (all P < 0.05)." (PMID 38566204, 2024). "Targeting CD96 in cancer may enhance the killing function of immune cells, thereby improving patient outcomes." (PMID 39655212, 2024). "Given that sCD155 has a higher binding affinity to DNAM-1 compared to TIGIT and CD96, sCD155 might have systemic effects, including regulation of immune responses toward circulating cancer cells or micrometastatic deposits." (PMID 38893071, 2024). "TIGIT, CD226 and CD96 are now broadly explored for possible targets of immunotherapy for cancer." (PMID 37568798, 2023). "However, future studies are needed to assess the potential role of CD96 as a target for cancer immunotherapy." (PMID 37629138, 2023). "Indeed, an increase in the efficacy of anti-PD-1 in combination therapy with anti-CD96 blocking mAbs have been observed in murine and human cancers." (PMID 37629138, 2023). "The expression of CD96 in most cancer tissues is higher than in paracancerous and normal tissues." (PMID 36674817, 2023). "The CD96+ cancer cell subpopulations exhibit features of both stemness and chemoresistance." (PMID 36581470, 2023). "CD96, a transmembrane checkpoint receptor of the immunoglobulin family, is normally expressed on the surface of NK cells and T cells and was previously shown to promote NK cell-mediated cancer cell cytolysis." (PMID 36109471, 2023). "CD96 is critical for immune function regulation, which participates in different immunological responses, controls immune cell infiltration, and affects the malignant properties of various cancer types." (PMID 37435058, 2023). "Based on this evidence, we can propose that targeting CD96 in cancer may enhance the killing function of immune cells, thereby improving patient outcomes." (PMID 36674817, 2023). "Therefore, even though CD96 function in NK cells is still debated, preclinical studies support the use of blocking anti-CD96 antibodies as a tool in anti-cancer therapy." (PMID 37760586, 2023). "CD96 is commonly expressed on the surface of CD8+ T cells and NK cells and has been implicated as an immune checkpoint inhibitor capable of suppressing IFNG production as well as cytotoxicity and worsening patient prognosis in cancer." (PMID 37177979, 2023). "Targeting CD96 that originates in immune cells has shown potential for cancer therapy." (PMID 36581470, 2023). "CD96, a new checkpoint receptor for cancer immunotherapy, may be a targeted receptor in T-cell and NK-cell biology for improving the immune response." (PMID 35646934, 2022). "Indeed, the roles of TIGIT and CD96 in NK cell depletion in various cancers are still under investigation, and further revelations are required to determine their potential as monotherapy or in combination with other checkpoints." (PMID 35606854, 2022). "Additionally, cell apoptosis and proliferation and inflammatory-related and cancer-related signaling pathways were significantly enriched through the gene with CD96 alterations." (PMID 36043142, 2022). "In glioblastoma patients, CD96 expression strongly correlated with cancer progression." (PMID 36231109, 2022). "In human cancer, a correlation of CD96 with T-cell markers and PD-1 was shown." (PMID 35406584, 2022). "Thus, further studies of the potential of CD96 as a target molecule for cancer immunotherapy are needed." (PMID 34433460, 2021). "CD96+ NK cells were found in PB of both healthy donors and patients with cancer and in the TME." (PMID 33572396, 2021). "This latest evidence would advocate against the use of CD96 blocking in cancer patients." (PMID 34503073, 2021).
cancer (continued). "Considering that CD96 was a significant risk factor for LGG and a distinct protective factor for SKCM, we identified LGG and SKCM as representative cancer types for subsequent analysis, with ACC serving as a control group since CD96 seemingly had no impact on ACC prognosis." (PMID 33680972, 2021). "CD96 significantly impacted the prognosis of diverse cancers." (PMID 33680972, 2021). "It is necessary to further explore the hypothesis by examining CD96 protein levels using a large sample size to confirm the role of CD96 in different cancers." (PMID 33680972, 2021). "Besides, we employed TIMER2.0 to exhibit the landscape of CD96 correlating with various immune infiltrates in human cancers." (PMID 33680972, 2021). "In general, CD96 was differentially expressed between most cancer and adjacent normal tissues." (PMID 33680972, 2021). "Overall, reports agree on CD96 being expressed on NK cells in the absence of disease; yet, it is unclear how activating stimuli or chronic inflammation such as occurring in cancer might alter CD96 expression levels." (PMID 34503073, 2021). "Besides, CD96 represents several unique features that exhibit profound beneficial effects in the coming age of human cancer therapy." (PMID 32695752, 2020). "As a novel immune checkpoint, CD96 is an attractive key target for cancer immunotherapy." (PMID 32695752, 2020). "CD96 is a rarely described surface receptor on NK cells, especially in cancers." (PMID 27626490, 2016). "Apart from providing more energy, there are also reports that FAO might protect cancer cells from chemotherapy-induced apoptosis by increasing the lipid synthesis on the mitochondrial membrane, or maintaining the cancer cell stemness via the CD96-Src-Stat3 signalling pathway." (PMID 38582885, 2024). "However, whether CD155 binding to cancer cell‐intrinsic CD96 directly participates in chemoresistance in solid tumors remains unknown." (PMID 36581470, 2023). "However, future work is still necessary to understand whether the engagement of the two different human isoforms results in different functional outcome and whether in cancer patients, CD96 can be targeted to improve immune surveillance." (PMID 37629138, 2023). "Finally, in mice, the combination of anti-CD96 mAb with other immune checkpoint inhibitors (i.e., CTLA-4 and PD-1) or chemotherapy (e.g., doxorubicin and gemcitabine) demonstrated to be beneficial, suggesting a supportive role for CD96 blockade in combination with other anti-cancer therapies." (PMID 33572396, 2021). "However, how CD96 correlating with immune infiltration and patient prognosis in pan-cancer remains unclear." (PMID 33680972, 2021). "Results of the current study showed an increased BTLA, CD96 and PD1 expression in cancer tissue samples and a significant positive correlation of BTLA and PD1 expression to the immune checkpoint CD96." (PMID 38928307, 2024). "Our results evidenced that the expression of cancer stem cell surface markers, including EPCAM, CSF3R, CD34, CD96 and ENG, were significantly different." (PMID 38977778, 2024). "Recently, attention has been drawn to receptors for nectin and nectin-like proteins as promising targets for cancer immunotherapy, including potential immune checkpoints as CD226, TIGIT, and CD96." (PMID 36674817, 2023). "The close relations of nectins to TIGIT, CD96 and CD226 make them an interesting target for immunotherapy of cancers." (PMID 37568798, 2023). "We also revealed six oncogenes that have been validated to be related to the poor prognosis of patients with cancer: CTSE, CALM1, PHGDH, IL9R, and CD96." (PMID 35433683, 2022). "Other potential immune checkpoints, such as LAG3, CD96, PDCD1, BTLA, IDO1, and TIGIT, were also enriched in PTPRD/PTPRT mutant cancers." (PMID 36248841, 2022).
cancer (continued). "By virtue of the clinical progression of TIGIT antagonists and emergence of novel CD96- and PVRIG-based approaches, our overall understanding of the ‘CD226 axis’ in cancer immunotherapy is starting to take shape." (PMID 35812451, 2022). "Along with its co-inhibitory receptor CD96 (TACTILE), TIGIT can bind to ligand CD155, also known as the poliovirus receptor (PVR), which is upregulated in many cancers." (PMID 33946954, 2021). "CD96 expression is positively correlated with the abundance of immune infiltrates, especially CD8+ T cells, DCs, macrophages, Tregs, and Tfh in various cancers." (PMID 33680972, 2021). "To further examine the prognostic potential of CD96, we used TCGA RNA-seq and clinical data downloading from UCSC Xena to analyze the prognosis of 33 TCGA cancer types." (PMID 33680972, 2021). "The results revealed that CD161 was positively correlated with marker genes of exhausted T cells, immune activating genes, and immunosuppressive genes in pan-cancer, such as TIGIT, PDCD1, LAG3, CTLA4, STING1, CD96, and IDO1." (PMID 34305920, 2021). "CD226, an activating receptor, competing the common ligand of CD155 with TIGIT and CD96, counterbalances the inhibitory CD96 and TIGIT receptors which are novel immune checkpoint targets for cancer immunotherapy." (PMID 33717085, 2021). "We found that CD161 was positively correlated with marker genes of exhausted T cells, immune activating genes, and immunosuppressive genes in pan-cancer such as TIGIT, PDCD1, LAG3, CTLA4, STING1, CD96, and IDO1." (PMID 34305920, 2021). "Dysregulation of the TIGIT/CD96/CD226/CD155 axis and NK cell function has been observed in certain cancers." (PMID 33946954, 2021). "Therefore, we supposed that CD96 could mediate similar immune functions in cancers." (PMID 33680972, 2021). "In addition, CD96-associated studies and clinical trials in human cancer patients are lacking." (PMID 34433460, 2021). "Surprisingly, we detected a significant reduction in activating receptors (CD16, NKG2D, NKp30, NKp44, NKp46, DNAM-1, CD96, or CD161) after co-cultivation with cancer cells compared to control NK cells." (PMID 31324057, 2019). "In the context of cancer cell surveillance and clearance, natural-killer group 2, member D (NKG2D), CD226 (DNAM-1) and CD96 (TACTILE) bind to ligands of cellular stress often overexpressed on malignantly transformed cells." (PMID 30908480, 2019). "Further, blocking CD96 reduced the number of B16F10 metastases in Tigit−/− mice compared to wildtype mice, indicating the synergistic potential of blocking CD96 and TIGIT in treating cancer." (PMID 31681269, 2019). "Although CD96 inhibitors have not been tested in clinical trials yet, pre - clinical evidence shows their effectiveness in preventing cancer metastasis in various mouse models." (PMID 40746529, 2025). "Furthermore, the regulatory network of MHC-II+ cancer cells revealed interactions between PVR and coinhibitory receptors including TIGIT and CD96, which induce CD8+ T-cell exhaustion and Treg activation, and subsequently facilitate immune evasion." (PMID 41281745, 2025). "Also, in most of the cancers, there was a significant correlation between UBE2C gene expression and CD96, CD274, CSF1R, KDR, and PDCD1LG2." (PMID 38577722, 2024). "Even though CD96 was discovered 20 years ago, its function is has not been completely unraveled especially related to immune response in cancer." (PMID 36674817, 2023). "In addition, CD96, CD244 have been identified as new checkpoint receptor targets for cancer immunotherapy, and TGFβ1 has been found to play a key role in the EMT process in ccRCC." (PMID 37679715, 2023). "Furthermore, the interaction between CD96 and CD155 promotes stemness and chemoresistance in cancer cells by activating Src‐Stat3‐Opa1‐mediated mitochondrial membrane remodeling, which subsequently regulates fatty acid β‐oxidation." (PMID 36581470, 2023).
cancer (continued). "Although strategies to neutralize the effect of CD96 are not as advanced as those developed for TIGIT, these studies undeniably demonstrate that the DNAM-1/TIGIT/CD96 axis and CD155 immunoregulation represent promising targetable immunotherapeutic strategies for cancer treatment." (PMID 36231109, 2022). "Mechanistically, we found the UQCRC1/eATP axis reduced the expression of chemokine CCL5 in cancer cells and altered the balance of activating receptor DNAM-1 and inhibitory receptor CD96 on NK-92MI cells, resulting in decreased chemotaxis and exhausted phenotype of NK-92MI cells." (PMID 35769718, 2022). "Both CD96 and NRP1 prevented cancer cells against the immune system, blocked them and could improve immunotherapy and help prevent cancer recurrence." (PMID 36144737, 2022). "A significant body of work from the Smyth group performed in various mouse cancer models suggests that CD96 might limit NK cell-mediated protection against metastases and, therefore, blocking CD96 would enhance NK cell production of IFN-γ and cancer control." (PMID 34503073, 2021). "NK cell immunoglobulin receptors CD226 and CD96 that interact with the nectin-like ligand CD112 and the polio-virus receptor CD155 on target cells are emerging as important mediators of NK cell anti-cancer functions." (PMID 30908480, 2019). "Regarding CD96, even though its role in humans remains controversial, preclinical studies demonstrate that the use of mAbs blocking CD96 interaction with CD155 may be exploited in anti-cancer therapy." (PMID 37629138, 2023). "As human CD96 contains both ITIM motifs and YXXM motifs, it is unknown whether the regulation of NK cells is co-activated or co-repressed, and what are its roles in distinct cancers." (PMID 36674817, 2023). "A better understanding of CD96 prognostic value in different cancer types as well as a better knowledge of CD96 signaling pathways in both NK cells and CD8+ T cells should help reconcile so far contradicting data and establish strategies to target this receptor in cancer patients." (PMID 34503073, 2021). "Similar to the CD28/CTLA-4 pathway, CD96 and TIGIT act as co-inhibitory receptors together with the co-stimulatory receptor CD226, which supports the contention that CD96 and TIGIT could be targeted for cancer immunotherapy." (PMID 32612110, 2020). "Moreover, we mainly employed TCGA database to perform these analyses, the included studies did not cover all previous published literatures involved CD96 and certain cancers, for instance, CD96 did not significantly related to LGG patient survival in GEO datasets by Prognoscan site." (PMID 33680972, 2021). "Additional studies employing anti-CD96 antibodies provided further support for targeting this pathway as a strategy to treat cancer; however, the findings were confounded by the observation that anti-CD96 antibodies need not block the CD155-CD96 interaction to exert their antimetastatic effect." (PMID 35998045, 2022). "Notably, although CD96 was also expressed by T cells, the control of metastases by an anti-CD96 mAb appeared to be dependent on NK cells, CD226 and IFN-γ production, suggesting a non-negligible role for NK cells in cancer immunotherapy." (PMID 31681269, 2019).